EZH2 (enhancer of zeste 2 polycomb repressive complex 2 subunit)
Diseases named in the same sentence as EZH2 in open-access papers (continued):
Sharing a sentence is not in itself a finding about the gene and the disease.
non-small cell lung carcinoma (115 papers, 2012 to 2026). A group of at least three distinct histological types of lung cancer, including non-small cell squamous cell carcinoma, adenocarcinoma, and large cell carcinoma. "For example, lncRNA prostate cancer associated transcript 6 promotes non-small-cell lung cancer cell growth, migration and invasion by repressing the expression of large tumor suppressor kinase 2 via binding with the epigenetic repressor EZH2." (PMID 35291911, 2022). "In non-small-cell lung cancer, we found that the expression of EZH2 is associated with poor prognosis." (PMID 33299862, 2020). "Prior studies have shown that miR-30b-5p promotes apoptosis and inhibits tumorigenesis in non-small-cell lung cancer via the EZH2 and PI3K/Akt pathways." (PMID 40732337, 2025). "In non-small cell lung cancer cells, the expression of cyclin D1 was significantly decreased after EZH2 silencing." (PMID 40028035, 2025). "Vascular endothelial growth factor A, a highly specific vascular endothelial growth factor promoting angiogenesis in tumorigenesis, is positively regulated by EZH2 through the PI3K/AKT signaling pathway to promote the growth of non-small cell lung cancer." (PMID 40028035, 2025). "MiR-138 directly targets and suppresses the expression of the enhancer of zeste homolog 2 (EZH2) gene in non-small cell lung cancer." (PMID 39376808, 2024). "LINC00511 functions as an oncogene by attaching to the histone methyltransferase, enhancer of zeste homolog 2 (EZH2), and inhibiting p57 in non-small cell lung cancer (NSCLC)." (PMID 39170516, 2024). "For example, elevated LINC01088-induced proliferation advantage depended on EZH2-mediated epigenetically inhibition of p21 expression in human non-small cell lung cancer." (PMID 35802620, 2022). "LncRNA X inactivate-specific transcript interacts with EZH2 to suppress transcription of its potential target kruppel like factor 2, thereby enhancing non-small-cell lung cancer cell proliferation, migration and invasion." (PMID 35291911, 2022). "On the other hand, circ-PRMT5 can down-regulate the expression levels of miRNA-377, -382 and -498 to enhance EZH2 expression, leading to an increase in proliferation of non-small cell lung cancer cells." (PMID 35236381, 2022). "On the other hand, KDM2B-mediated demethylation of H3K4me3, along with KDM6A-mediated demethylation of H3K27me3, has been found to promote EZH2 expression and the subsequent progression of non-small cell lung cancer." (PMID 34266408, 2021). "Upregulating SNHG20 promotes cell proliferation and migration by epigenetically silencing of P21 expression through EZH2 in non-small cell lung cancers." (PMID 34811354, 2021). "Altogether, our data indicated that HOTAIR regulates cell cycle progression through epigenetic regulation of EZH2/H3K27 in non-small cell lung cancer cells." (PMID 34405017, 2021). "In non-small cell lung carcinoma LINC01133 suppresses the transcription of CDKN1A (p21) via a direct EZH2-mediated chromatin remodeling mechanism." (PMID 34445100, 2021). "This shows that the high expression of EZH2 “juvenizes” tumor cells, thereby affecting the prognosis of non-small-cell lung cancer." (PMID 33299862, 2020). "EZH2 high expression or its synergistic action with KRAS and BRAF mutations affects the prognosis of non-small-cell lung cancer." (PMID 33299862, 2020). "For instance, Xist acts as an oncogene in non-small cell lung cancer by recruiting EZH2 to the epigenetically repressed kruppel-like factor 2 gene (KLF2)." (PMID 33392092, 2020). "Since EZH2 and KDM6B have been both associated with EMT and aggressiveness in independent cancer models, we first analyzed their expressions in NSCLCs (Non Small Cell Lung Carcinomas)." (PMID 33291363, 2020). "LncRNA 00511 acts as an oncogene in non-small-cell lung cancer (NSCLC) via binding to EZH2 and suppressing p57." (PMID 32425696, 2020).
non-small cell lung carcinoma (continued). "For example, it can promote non-small cell lung cancer cell proliferation by recruiting EZH2 to the large tumor suppressor kinase 2 (LATS2) promoter and represses LATS2 transcription." (PMID 29244840, 2017). "LncRNA LINC00511 functions as a scaffold associated with EZH2/PRC2 complexes and regulates their localization to suppress expression of p57 in non-small-cell lung cancer (NSCLC) cells." (PMID 28561778, 2017). "Loss of long noncoding RNA FOXF1-AS1 regulates epithelial-mesenchymal transition, stemness and metastasis of non-small cell lung cancer cells via EZH2." (PMID 29050269, 2017). "Nevertheless, BM-MSCs-exo which carried miR-30b-5p showed potential in decreasing EZH2 expression, inhibiting tumor cell proliferation, migration, and invasion, and inducing apoptosis, thereby restraining the development of tumors in a non-small-cell lung cancer model." (PMID 40732337, 2025). "Furthermore, the overexpression of EZH2 attenuated FAK-inhibition-induced cellular senescence in non-small cell lung cancer cells." (PMID 36009484, 2022). "EZH2 is involved in gefitinib resistance in non-small cell lung cancer." (PMID 36471952, 2022). "To further verify the critical role of EZH2 in FAK-mediated anti-senescence signaling, we explored whether EZH2 overexpression bypasses FAK-inhibition-induced cellular senescence in non-small cell lung cancer cells." (PMID 36009484, 2022). "We examined whether EZH2 acts as a critical regulator of a master anti-senescence signaling pathway in non-small cell lung cancer cells." (PMID 36009484, 2022). "However, in non-small cell lung cancer miR-4465 was suggested to play a suppressive role by decreasing the expression of the oncogene EZH2." (PMID 33653966, 2021). "Thus, TUG1/EZH2/EED complex inhibits the proliferation of non-small cell lung cancer by binding to the promoter of CUGBP and Elav-like family member 1 (CELF1) and repressing it." (PMID 33050646, 2020). "Additionally, circ-PRMT5 can upregulate EZH2 via sponging miR-377-382-498 in non-small cell lung cancer (NSCLC)." (PMID 31963578, 2020). "MiR-138 inhibits tumor growth by inhibiting EZH2 in non-small cell lung cancer." (PMID 33718109, 2020). "We believe that the mechanism of high expression of EZH2 on non-small-cell lung cancer may be related to the KRAS and BRAF pathways." (PMID 33299862, 2020). "H19/EZH2 complex silenced PTEN thus stimulates the migration of non-small cell lung cancer." (PMID 33050646, 2020). "In addition, 3-deazaneplanocin A, an inhibitor of the histone methyltransferase EZH2, inhibits the growth of non-small cell lung cancer cells." (PMID 30764831, 2019). "In non-small cell lung cancer cells, miR-21 overexpression also enhanced EZH2 expression via an unknown mechanism and promoted cell invasion and migration." (PMID 34991274, 2018). "In addition, epigenetic silencing of the lncRNA SPRY4 occurs in non-small cell lung cancer cells through direct transcriptional repression mediated by EZH2." (PMID 26848980, 2016). "Cao and colleagues have reported that p21 could be significantly increased in non-small cell lung cancer cells after EZH2-siRNA delivery." (PMID 24155936, 2013). "EZH2 has been detected in tumors with various origins, such as urothelial carcinoma, squamous cell carcinoma of the esophagus, gastric cancer, glioma, renal cell carcinoma, non-small cell lung carcinoma (NSCLC), colorectal carcinoma and breast cancer." (PMID 22809481, 2012). "EZH2 may be a new target for the treatment of non-small-cell lung cancer." (PMID 33299862, 2020). "However, the mechanism that EZH2 played in promoting malignancy in non-small cell lung cancer (NSCLC) remains unclear." (PMID 23300840, 2012). "In non-small cell lung cancer (NSCLC), it serves as a molecular scaffold that physically recruits epigenetic repressors EZH2 and LSD1." (PMID 40863724, 2025).
non-small cell lung carcinoma (continued). "We show that YAP and TAZ cooperate with EZH2, and MYC to transcriptionally repress onco-suppressor genes, including PTEN, in non-small cell lung cancer (NSCLC) cells." (PMID 39455556, 2024). "As for SMARCA4, in non-small cell lung cancer, SMARCA4 deletion is sensitive to combination of etoposide and DZNep (EZH2 inhibitor)." (PMID 38427070, 2024). "YAP and EZH2 act cooperatively to impair the tumor suppressor activity of TGFBR2 in non-small cell lung cancer, and the interaction between YAP and EZH2 participates in the transcriptional repression of key cell cycle regulators." (PMID 38245781, 2024). "By suppressing p21 by binding to EZH2, LINC01088 can enhance cell proliferation, ultimately aggravating the tumorigenicity of non-small cell lung cancer (NSCLC)." (PMID 36983670, 2023). "LINC00511 downregulates LATS2 and KLF2 by combining EZH2 and LSD1 to promote the proliferation, migration, and invasion of non-small-cell lung cancer." (PMID 35664432, 2022). "In non-small cell lung cancer, LINC00665 upregulates EZH2, an important component of the initiation complex (PRC2), thereby activating the PI3K/AKT signaling pathway and mediating EGFR expression, weakening the inhibition of EGFR kinase by the drug gefitinib." (PMID 35563845, 2022). "In non-small cell lung cancer, EZH2-mediated H3K27me3 has been demonstrated to bind directly to the promoter region of PTEN, but how EZH2 regulates PTEN in CKD requiring further research." (PMID 35559246, 2022). "In human non-small cell lung cancer (NSCLC), LINC01088 accelerates cell growth through scaffolding Enhancer Of Zeste 2 Polycomb Repressive Complex 2 Subunit (EZH2) and lessening p21." (PMID 35392763, 2022). "Homoplastically, lncRNA LINC00665 was confirmed to induce acquired resistance to gefitinib through recruiting EZH2 and activating PI3K/Akt pathway in non-small-cell lung cancer." (PMID 34454479, 2021). "In non-small cell lung cancer, similar to lncRNA HOTTIP, lncRNA AGAP2-AS1 reduces apoptosis by interacting with EZH2 and LSD1 to repress LATS2 and KLF2 expression." (PMID 33050646, 2020). "EZH2 enhances cell cycle progression and activating VEGF / AKT signaling in non-small cell lung cancer (NSCLC) cells." (PMID 32859239, 2020). "In non-small-cell lung cancer, HOXA11-AS guides EZH2 and DNMT1 proteins to the promoter region of miR-200b and blocks miR-200b transcription." (PMID 31757938, 2019). "In non-small-cell lung cancer cells, upregulated long non-coding RNA AGAP2-AS1 represses LATS2 and KLF2 expression through interacting with EZH2 and LSD1." (PMID 29050269, 2017). "A recent study indicated that long non-coding RNA LINC01133 repressed KLF2, P21 and E-cadherin transcription through binding with EZH2, LSD1 in non small cell lung cancer." (PMID 29113337, 2017). "From our in-house RNAseq data, we found that 60 out of 66 patients’ non-small cell lung cancer tissues had overexpressed EZH2 mRNA relative to the matched noncancerous lung tissues (average non-small cell lung cancer/noncancerous ratio of 6.27 ± 1.23)." (PMID 37992808, 2024). "In addition, the LINC00665/EZH2/CDKN1 C axis enhances the proliferation, migration, and sensitivity of non-small cell lung cancer cells to the chemotherapeutic drug cisplatin (DDP)." (PMID 35563845, 2022). "EZH2 overexpression significantly suppressed PF-573228-treatment-induced cellular senescence in A549 and H1299 cells, indicating that EZH2 acts as a critical downstream effector of FAK-mediated anti-senescence programming in non-small cell lung cancer cells." (PMID 36009484, 2022). "The ectopic expression of EZH2 alleviates FAK-inhibitor-induced cellular senescence in non-small cell lung cancer cells, further supporting the hypothesis that the FAK–EZH2 axis regulates senescence programming." (PMID 36009484, 2022).
non-small cell lung carcinoma (continued). "LINC00665 is upregulated in non-small cell lung cancer and can activate the PI3K/AKT pathway by increasing the stability of EZH2, an important component of the initiation complex (PRC2), and mediates the expression of EGFR, thereby counteracting the effect of gefitinib." (PMID 35563845, 2022). "EZH2 could result in a diminished level of Krüppel-like factor 2 (KLF2) in multiple cancers such as cervical cancer and non-small cell lung cancer." (PMID 34462420, 2021). "EZH2, interacting with lncRNA X-inactive specific transcript, could lead to suppression of KLF2 transcription in non-small cell lung cancer." (PMID 34462420, 2021). "The pseudogene DUXAP8 may act as an oncogene in non-small cell lung cancer, and it may play this role by silencing EGR1 and RHOB transcription via binding with EZH2 and LSD1." (PMID 33711952, 2021). "Both tazemetostat (EZH2 inhibitor) and gefitinib (a histone lysine demethylases inhibitor) have been recently approved by the FDA for the treatment of epithelioid sarcoma and non-small cell lung cancer (NSCLC) respectively." (PMID 33066013, 2020). "lncRNA AGAP2-AS1 could bind with EZH2 and LSD1 and recruit them to KLF2 and LATS2 promoter regions to repress their transcription in non-small-cell lung cancer." (PMID 30069164, 2018). "It was also reported that the upregulation of the long non-coding RNA AGAP2-AS1 facilitates cell proliferation, migration and invasion, and inhibits cell apoptosis; it also represses LATS2 and KLF2 expression through its interaction with EZH2 and LSD1 in non-small-cell lung cancer cells." (PMID 27906682, 2017). "This study aimed to evaluate the relationships between c-MYC and EZH2 immunohistochemical expression and survival in patients with small cell lung carcinoma (SCLC) and non-small cell lung carcinoma (NSCLC)." (PMID 41928013, 2026). "For example, lncRNA AGAP2-AS1 has been demonstrated to recruit the enhancers of zeste homolog 2 (EZH2) and LSD1 to the promoter regions of KLF2 and large tumor suppressor 2 (LATS2), thus suppressing the transcription of KLF2 and LATS2 and promoting the progression of non-small cell lung cancer." (PMID 38516191, 2024). "Moreover, EZH2-mediated H3K27 methylation attenuates the expression of TIMP-2 and TIMP-3 by inducing promoter DNA methylation in prostate cancer while the silencing of E-cadherin occurs through H3K27 methylation without DNA methylation in non-small-cell lung carcinoma." (PMID 35559246, 2022).
epithelioid sarcoma (107 papers, 2020 to 2026). An aggressive malignant neoplasm of uncertain differentiation, characterized by the presence of epithelioid cells forming nodular patterns. "Other notable targets being investigated in the STS realm include NTRK fusion in CD34-positive fibrosarcomas of bone and soft tissue, EZH2/INI1 loss (epithelioid sarcomas, rhabdoid tumors), and ALK fusion in inflammatory myofibroblastic tumors." (PMID 40075735, 2025). "The polycomb repressive complex EZH2 inhibitor tazemetostat was recently approved for the treatment of SMARCB1-deficient epithelioid sarcomas, based on the functional antagonism between PRC2 and SMARCB1." (PMID 40794452, 2025). "EZH2 inhibition is an effective therapeutic strategy in epithelioid sarcomas that have a loss of SMARCB1, a subunit of SWI/SNF complex that opposes the activity of EZH215." (PMID 39789291, 2025). "Loss of INI1 expression leads to oncogenic activation of EZH2 (an enzyme that catalyzes trimethylation of histone H3 lysine 27, H3K27me3), especially in epithelioid sarcoma." (PMID 34315468, 2021). "An EZH2 inhibitor, tazemetostat, just gained approval for treatment of epithelioid sarcoma harboring SMARCB1 loss in January 2020 in the USA." (PMID 33481850, 2021). "A mutation in the INI1 suppressor gene in epithelioid sarcoma cells causes deregulation of EZH2 that leads to the activation of multiple oncogenic signaling pathways." (PMID 32722580, 2020). "Besides targeting the genomic alteration, epigenetic regulators such as DNA methylation, histone modification and microRNA are emerging potential targets against sarcomas including tazemetostat, an EZH2 inhibitor for epithelioid sarcoma with loss of SMARCB1/INI1/BAF47." (PMID 38434982, 2024). "EZH2 inhibitors (EZH2is) gained attention after the first-in-class drug Tazemetostat received FDA approval for treating epithelioid sarcoma." (PMID 41898517, 2026). "The second agent we employed in this study is tazemetostat, which is a first‐in‐class US Food and Drug Administration (FDA)‐approved oral EZH2 inhibitor for FL and epithelioid sarcoma (ES)." (PMID 40464712, 2025). "EZH2 mutations have emerged as important therapeutic targets in cancer, with the EZH2 inhibitor tazemetostat gaining FDA approval in 2020 for the treatment of patients with advanced epithelioid sarcoma and follicular lymphoma." (PMID 39984702, 2025). "Tazemetostat, an oral EZH2 inhibitor, is approved for treating epithelioid sarcoma, and is under investigation for other cancers." (PMID 40042761, 2025). "The EZH2 inhibitor Tazemetostat has been approved for treating epithelioid sarcoma, and other small-molecule inhibitors have shown enhanced anticancer efficacy when combined with other therapies." (PMID 40042761, 2025). "Food And Drug Administration (FDA) has recently approved the EZH2 inhibitor tazemetostat for treating epithelioid sarcoma." (PMID 38961535, 2024). "In epithelioid sarcoma, EZH2 is constitutively active due to the inactivation of the SWI/SNF chromatin remodeling complex, which functions antagonistically to EZH2 by promoting active transcription through chromatin decompaction." (PMID 38473997, 2024). "Tazemetostat (EPZ‐6438) is a clinically advanced EZH2 inhibitor that has therapeutic efficacy against B‐cell non‐Hodgkin lymphoma and epithelioid sarcoma in several early Phase (I–II) clinical trials." (PMID 39501501, 2024). "Tazemetostat, a specific EZH2 inhibitor, has just been approved for patients with advanced epithelioid sarcoma and represents a new therapeutic option for this disease." (PMID 38434982, 2024). "Tazemetostat is a potent and highly selective EZH2 inhibitor, which showed clinical activity in epithelioid sarcoma, a chemotherapy-resistant histotype." (PMID 37998367, 2023). "The FDA has approved EZH2 inhibitor Tazemetostat for epithelioid sarcoma, the first approval of an epigenetic drug for solid tumor." (PMID 38268926, 2023).